TNF (tumor necrosis factor)
Diseases named in the same sentence as TNF in open-access papers (continued):
Sharing a sentence is not in itself a finding about the gene and the disease.
colitis (continued). "Induction of colitis caused more than 8-fold increase in concentration of IL-1β and more than 6-fold increase in concentration of TNF-α in colonic mucosa." (PMID 27433160, 2016). "TNF-α, IL-1, and IL-6 have been demonstrated to promote colorectal and colitis-associated tumor development." (PMID 27388564, 2016). "Using an anti-CD146 antibody, AA98, alone or together with an anti-TNF-α antibody significantly attenuated colitis and prevented colitis-associated colorectal carcinogenesis in mice." (PMID 26839731, 2015). "Our data demonstrate a pathogenic role for TNF in acute TNBS colitis and importantly, we show for the first time how inflammation (and TNF production) is associated with significant differences in the microbiota." (PMID 25775453, 2015). "This is in good agreement with data showing that Dmbt1−/− mice were more susceptible to colitis and showed elevated mRNA levels for IL-6 and TNF during inflammation." (PMID 25885541, 2015). "It has been demonstrated that colitis in both humans and mice is associated with increased levels of cytokines such as TNF-α, IL-6, IL-12p70 and IL-23." (PMID 24722235, 2014). "Treatment with a DP receptor agonist alleviated colitis and suppressed tumorigenesis in association with decreased TNF-α expression." (PMID 25594036, 2014). "Systemic deficiency in H-PGDS aggravated colitis and accelerated tumor formation accompanied by increased TNF-α expression." (PMID 25594036, 2014). "We have previously demonstrated that this pathway also occurs in vivo in an animal model of DSS-induced colitis and TNF-induced arthritis and that loss of SK1 prevents COX2 induction in both of these murine models of inflammation." (PMID 25460165, 2014). "In contrast to the failure of rivastigmine to reduce TNF-α in the colon of mice with DSS colitis, 1 and 2 mg/kg of the drug caused a similar reduction of more than 70% in TNF-α in the colon of rats with DNBS-induced colitis." (PMID 23469045, 2013). "In vitro studies indicate that guanylin production is specifically and profoundly diminished by TNFα and this is consistent with the loss of guanylin expression IL-10−/− colitis." (PMID 24244444, 2013). "DSS induced colitis also caused a 2-fold increase in the expression of TNF-α mRNA and 4- and 5- fold increases in the expression of IL-6 and IL-1β, respectively." (PMID 23469045, 2013). "Our studies were unable to separate the effects of TNF deficiency on the mucosal barrier of T/I mice from those of inflammation, due to the early spontaneous development of colitis in T/I mice." (PMID 22848611, 2012). "Our recent study has shown that TNF signaling via TNF-R1or TNF-R2 play a pathogenic role in TNBS-induced colitis." (PMID 23285227, 2012). "The exact role of TNF signaling via TNF-R1 or 2 in the course of DSS colitis in other strains and underlying mechanisms, however, remains poorly understood." (PMID 23285227, 2012). "Some mice that were heterozygous for TNF deficiency (T-het/I mice) also developed colitis soon after weaning, but were significantly less likely to do so compared with T/I mice (relative risk 0.39, 95% confidence interval 0.22–0.68; p = 0.0004)." (PMID 22848611, 2012). "The effect of TNF blockade or deficiency in the DSS murine model of colitis is particularly instructive." (PMID 22434667, 2012). "Here, we will summarize the actions of TNF and chemokines in tumor biology and discuss their potential contribution to colitis-associated carcinogenesis." (PMID 24212934, 2011). "The expression of TNF and chemokines is aberrantly expressed in a mouse model of colitis-associated carcinogenesis as well as in inflammatory bowel disease and colon cancer in humans." (PMID 24212934, 2011). "We show that NK cell subsets and neutrophils, compared to T cells, expressed the greatest levels of TNF-α during Mycobacteria-mediated colitis, which is also a hallmark of spontaneous murine colitis." (PMID 18533024, 2008).
colitis (continued). "LMP-420 treatment also reduced (-85%) TNF elevations associated with acute DSS colitis to near baseline levels." (PMID 18331642, 2008). "We therefore conclude that IL-32 is closely associated with TNFα, and contributes to the exacerbation of TNFα-related inflammatory arthritis and colitis." (PMID 17078892, 2006). "Inflammatory cytokines such as IL-17 and TNF-α are closely linked to the progression of colitis." (PMID 40502390, 2025). "Notably, in the mouse mastitis model, mastitis was associated with colitis and systemic inflammatory response, as evidenced by elevated IL‐6, TNFα, and IL‐1β levels in circulation and colonic tissues (P < 0.01)." (PMID 40552401, 2025). "In the context of inflammation during DSS-induced colitis, we observed elevated levels of TNF that may underlie the increased baseline neuron activity observed 53, aligning with evidence that intestinal inflammation activates vagal afferents and the NTS54–56." (PMID 40268933, 2025). "Moreover, Sphingomonas, another microorganism positively associated with IL-6 and TNF-α in our study, was identified as more abundant in the gut of patients with colitis-associated cancer and in an inflammation-associated animal model." (PMID 41154794, 2025). "The recovery was associated with a sharp drop in local TNFα concentration, which in all groups subjected to the induction of experimental colitis except the PC group of BALB/c mice (PC vs. NC p ˂ 0.005 for BALB/c) reached a level comparable to the one recorded in corresponding NC." (PMID 38892639, 2024). "In addition, intestinal ERβ expression prevent the development of colitis‐associated CRC by regulating the expression of TNFα, a regulator of NFκB signaling network." (PMID 36207986, 2023). "The colitis was exacerbated in these animals, as evidenced by a reduced colon length associated with increased colonic mRNA expression and protein levels of IL-1β, IL-4, IL-12, IL-13, IFNγ and TNF-α." (PMID 37996842, 2023). "To further understand the protective efficacy of PS, we analyzed the content of colitis-associated inflammatory cytokines and found that pretreatment with PS reduced the levels of pro-inflammatory cytokines, such as IL-1β, TNF-α, and IL-6, while increased anti-inflammatory TGF-β1 cytokine levels." (PMID 37447380, 2023). "Colitis-associated myeloid cells have higher expression of genes involved in innate inflammatory pathways, suggesting that pathology is driven by inflammasome activation and production of IL-1β, IL-6, and TNFα." (PMID 37461742, 2023). "Furthermore, FADD deletion in IECs results in RIPK3-dependent necroptosis of IECs and colitis which are strongly reduced in TNF- or TNFR1-deficient mice." (PMID 38020877, 2023). "In addition, the administration of infliximab, an anti-TNFα mAb, for immune-related adverse events, such as colitis, associated with the administration of immune checkpoint inhibitors to patients with tumors is expected to increase in the future." (PMID 36996146, 2023). "Elevated IL‐4 and miR‐324‐5p levels in tumour microenvironment caused a decreased expression level of CUEDC2 in tumour‐associated macrophages, which resulted in excessive levels of proinflammatory cytokines, such as TNF‐α and IL‐6, and linked with both colitis and colon carcinogenesis." (PMID 37138536, 2023). "Earlier reports also revealed that blocking TNF-α, IL-1β, or IL-6 caused an anti-colitis effect." (PMID 37509556, 2023). "TNF-a inhibitors are commonly used to treat ICB-associated colitis, and it has been reported that TNF-a inhibition may improve the safety profile of checkpoint inhibitor therapy without decreasing its efficacy." (PMID 37046745, 2023). "Mice overexpressing the TNF-α gene are more susceptible to chronic TNBS-induced colitis." (PMID 36926182, 2023). "Additionally, the correlation of the expression of pro-inflammatory cytokines, such as IL-1β and TNF-α with colon inflammation caused by Clostridium sensu stricto 1, has been observed." (PMID 36432504, 2022).
colitis (continued). "In contrast, another murine homolog SIGN-R3 can recognize carbohydrate ligands on commensal fungi, and the SIGN-R3-deficient mice exhibit more severe colitis symptoms (such as weight loss and diarrhea) with increased TNF-α production in colon compared to wild-type mice." (PMID 35619716, 2022). "Pg implantation in the rectum induced overexpression of TNF-α and IL-6, followed by loss of surface epithelium, destruction of crypts, and infiltration of inflammatory cells, thereby exacerbating the clinical symptoms of colitis in this mouse model." (PMID 35056032, 2022). "It showed that the level of IL-1β and TNF-α was also increased in colitis-associated cancer." (PMID 36016583, 2022). "Seemingly paradoxical, TNF‐α–/– mice are more susceptible to DSS‐induced colitis." (PMID 35593111, 2022). "Moreover, the inflammatory process associated with colitis increases the production of inflammatory cytokines, mainly TNF and IL-6." (PMID 35295931, 2022). "While in CC patients, TNF has been associated with DNA damage and carcinogenesis, TNF secretion by IECs in murine models of colitis has been shown to participate in the initiation of chronic inflammation, suggesting that epithelial barrier responses are crucial for disease pathogenesis." (PMID 36555145, 2022). "Whether NO neurotoxicity from microglia occurs in the CNS of colitis models is yet to be explored, but TNBS-induced colitis was associated with a significant increase in hippocampal TNF-α and iNOS protein levels which could reflect reactive microglia activity." (PMID 34983592, 2022). "TNF-α is associated with the pathogenesis of colitis since is increased in inflamed colon tissue." (PMID 35628865, 2022). "The monoclonal antibodies targeting M1-associated cytokines TNF-α, including infliximab and adalimumab, have been approved to treat moderate to severe colitis in clinic, while patients with the M2-related factor IL-10 receptor deficiency have enhanced susceptibility to severe colitis." (PMID 33868286, 2021). "TNF-α inhibition has been shown to overcome anti-PD-1 resistance in a murine model and infliximab has been associated with a trend toward increased survival in melanoma patients with ipilimumab colitis." (PMID 33407605, 2021). "Interestingly, DSS-induced colitis in miR-21 deficient mice was decreased compared to that in wild type mice and had reduced levels of TNF- α." (PMID 33647883, 2021). "In support of the possibility that colitis-associated inflammatory factors contribute to neuroinflammation, we observed increased plasma concentrations of TNFα, MCP-1/CCL2, IL-6, and IFNγ in colitic mice, as well as increased transcription of Tnf, Il1b, and Il6 in their brains." (PMID 34511110, 2021). "In a TPH1 knock out (TPH1(−/−)) colitis mice model, that lack 5-HT produced by ECs, it was found that macrophage infiltration, IL-1β, IL-6, and TNFα production and colitis-associated colonic tissue damage were significantly reduced compared to the control (TPH1(+/+)) mice." (PMID 33807994, 2021). "Moreover, TNF inhibitor enalapril or anti-TNF monoclonal antibody decreased the risk of hepatitis and colitis induced by double checkpoint inhibition." (PMID 34367136, 2021). "TNF-α levels are a hallmark index of colitis, particularly for UC." (PMID 33946346, 2021). "Additionally, chemerin aggravated the severity of colitis by causing extensive damage to the intestinal mucosa and increased pro-inflammatory cytokine levels in colon cells, including IL-6, TNF, and IFN-γ." (PMID 34640632, 2021). "In DSS-induced colitis in mice, digestion of preserved egg white ameliorated clinical symptoms, such as weight loss, disease activity index and inhibited secretion of pro-inflammatory cytokines TNF-α and IL-6." (PMID 33806061, 2021). "TNFα induces colitis-associated CRC through the NF-κB pathway." (PMID 34220337, 2021).
colitis (continued). "Also, TNF-α and IL-6 contribute immensely to loss of body weight in colitis by releasing neuropeptides that suppress appetite and precipitate cachexia." (PMID 32090060, 2020). "This study tested the hypothesis that deletion of the Aicda gene could protect against the development of inflammation-associated colorectal cancers, using a model of UC-like colitis in “T/I” mice deficient in TNF and IL10." (PMID 32941525, 2020). "The prevention of intestinal mucosal barrier injury observed in pioglitazone-treated mice with colitis was also associated with increased expressions of tight junction proteins and reduced protein levels of TNF-α, IL-6, and MMP9, which are soluble mediators controlled by the ERK-NF-κB." (PMID 31989391, 2020). "Nrf2-deficient mice were susceptible to DSS-induced colitis, because of the reduced levels of antioxidative enzymes, including HO-1, along with the elevated levels of the pro-inflammatory mediators, including IL-6, TNF-α, iNOS and COX-2." (PMID 32290483, 2020). "Importantly, administration of this compound in a rat model of oxazolone-induced colitis limited weight loss and decreased levels of TNF-α in colonic tissue." (PMID 33072065, 2020). "Additionally, zinc deficiency was associated with increased LPS-induced TNF-α and IL-10 concentrations in mesenteric leukocytes isolated from rats with dextran sulfate sodium induced colitis." (PMID 32231139, 2020). "Consequently, TNFR deficiency or the treatment of wild type mice with the specific pharmacological inhibitor of TNF, etanercept, markedly reduces colitis-associated colon cancer." (PMID 31316505, 2019). "We found that there were 15 analytes upregulated in both DSS and C. rodentium colitis, including innate immune cell-associated cytokines (G-CSF, IL-1β, TNF-α, LIF, and IL-6), chemokines (CCL2, CCL5, CCL11, CXCL2, CXCL8, CXCL9, MIP-1α, and MIP-1β), and Th1 (IFN-γ) and Th17 (IL-17) cytokines." (PMID 30972302, 2019). "The results reported here suggests that oral administration of Lactococcus lactis carrying the eukaryotic expression vector coding for an anti-TNFα induces a reduction of colitis associated inflammatory and histopathological markers suggesting an amelioration in disease." (PMID 31238939, 2019). "To verify the hypothesis that Ct55 may function in colitis-associated colorectal cancer by targeting TNF-α-induced NF-κB signaling, we detected the expression levels of p-p65 and other indicated proteins by western blot." (PMID 30944312, 2019). "In addition to providing protection from the key proinflammatory cytokine TNF-α, IL-10 also regulates chronic intestinal inflammation, so colitis of high severity occurs when low IL-10 levels are associated with intestinal endoplasmic reticulum (ER) stress." (PMID 30915354, 2019). "Although, under acute colitis conditions induced by dextran sulfate sodium, TNF-deficient mice and mice treated with anti-TNF exhibit enhanced intestinal inflammation, whereas, in mice with chronic inflammation, anti-TNF treatment reduces colitis." (PMID 30591653, 2018). "Indeed, M2-associated genes (Arg1, IL-10, Fizz1, and Mrc1) were increased and M1-associated genes (IL-1β, IL-6, IL-12, and TNF-α) were decreased in colons of DSS colitis miR-155−/− mice." (PMID 29774026, 2018). "TNF is crucial for the initiation and progression of colitis-associated colon carcinogenesis." (PMID 29740162, 2018). "Maternal high-fat diet consumption enhances offspring susceptibility to dextran sulfate sodium-induced colitis in mice accompanied with upregulated NF-κB signaling, enhanced neutrophil infiltration, and elevated IL-6 levels, thereby further revealing TNFα and IL-6 as ideal targets for CRC therapies." (PMID 30591653, 2018). "Furthermore, it has been demonstrated that TNF-α can promote colitis-associated CRC, a long-term consequence of IBD." (PMID 29118756, 2017).
colitis (continued). "We hypothesized that TLR4 expression is upregulated in colitis associated tumors and plays a pivotal role to induce iNOS and TNF-α expression through NF-κB pathway." (PMID 28408791, 2017). "The underlying colitis is characterized by high levels of inflammatory cytokines, including TNFα." (PMID 28796256, 2017). "Moreover, many DSS induced colitis drugs, including TNF-α blockers, are associated with opportunistic infections, malignancies and autoimmunity." (PMID 27258062, 2016). "Interestingly however, treatment with dextran sulfate sodium (DSS) causes an increased accumulation of DSS and TNF production in intraluminal cells and rapid destruction of the inner mucus layer, resulting in increased severity of colitis in mutant mice." (PMID 27229483, 2016). "It is possible that alterations were not identified because the model used in this study is for mild UC and upregulation of proinflammatory cytokines, such as IFN-γ and TNF-α, was observed more consistently in severe inflammation, such as colitis associated with carcinogenesis." (PMID 27957238, 2016). "Thus, as we have seen in TNBS-induced experimental colitis, a decrease in Cav-1 levels results in a higher TNF output, possibly due to a loss of TLR4 regulation." (PMID 25756273, 2015). "In the present work, we provide clear experimental evidence that maternal inflammation has no impact on the offspring's risk to develop genetically-driven ileitis and colitis, despite the fact that TNF-driven maternal ileitis extensively modulates transcriptional responses in the fetal epithelium." (PMID 24849654, 2014). "Heparanase was shown to stimulate macrophage activation, which in colitis induces production (i.e., via TNFα) and activation (via cathepsin L) of latent heparanase in the colon epithelium, together generating a vicious cycle that powers colitis and the associated tumorigenesis." (PMID 24465803, 2014). "Pro-tumorigenic cytokines such as IL-1β, IL-6 and MIP-2 production as well as INF-γ and TNF production at the lamina propria were increased in the setting of colitis, and further in tumor tissues in associations with up-regulated TNFR2 and MLCK expressions in the epithelial cells of a CAC model." (PMID 24520376, 2014). "Moreover, the induction of experimental colitis by TNBS or dextran sulfide administration caused a significant increase in the TNF-content in the colonic mucosa and submucosa." (PMID 24877092, 2014). "Consistently, we found that the TTP KO mice treated with DSS displayed increased susceptibility to colitis, decreased colon length, and increased neutrophil infiltration and expression of pro-inflammatory cytokines such as TNF-α, IL-6, CXCL1, and CXCL2 in the large intestinal mucosa." (PMID 24586391, 2014). "With regard to the therapeutic mechanism, previous studies have reported that administration of recombinant HGF protein and vector encoding HGF gene ameliorate TNBS-induced colitis and reduced inflammation, decreasing the levels of inflammatory cytokines such as TNF-α." (PMID 24604303, 2014). "Finally, DSS-induced colitis is severely reduced in mice in whom Ly6Chi monocytes are deficient in TNFα production." (PMID 24726741, 2014). "In fact, mice deficient in TNFα or TNFRI-signaling are more susceptible to DSS-induced colitis." (PMID 23977323, 2013). "In syndecan-1-deficient mice after colitis induction, delayed skin and corneal wound healing, functionally adverse repair, prolonged recruitment of inflammatory cells, and significant upregulation of TNFα were detected." (PMID 23874391, 2013). "Using the AOM + DSS model, Hyun and colleagues showed that IL-17A-deficient mice developed a less severe colitis than wild-type mice, as demonstrated by the decreased cell infiltrate and the diminished expression of pro-inflammatory factors (e.g., TNF-α, IL-6)." (PMID 23109839, 2012).